HIF1A (hypoxia inducible factor 1 subunit alpha)
Diseases named in the same sentence as HIF1A in open-access papers (continued):
Sharing a sentence is not in itself a finding about the gene and the disease.
tumor (continued). "Together, our data indicated that the hypoxic tumor microenvironment contributes to the upregulation of NAT10 in GC and that NAT10 transcription is regulated by HIF‐1α." (PMID 37328448, 2023). "Increased Trx-1 gene expression correlated with HIF-1α levels in cancer cells, resulting in higher VEGF production and promoted tumor angiogenesis." (PMID 36831579, 2023). "HIF1α, NRF2, and other redox control regulators are naturally activated under hypoxia and control tumour progression, aggressiveness, and its response to treatment." (PMID 36769044, 2023). "First, 49 specimens of IBC tumor tissues and 33 samples of normal tissues were tested for the expression of OCN and HIF‐1α." (PMID 36971046, 2023). "Hypoxia-inducible factor 1-alpha (HIF-1α) and NF-κB mediators, including cytokines, matrix metalloproteinase (MMP) and oncogenes, increase the VEGF production and support tumour angiogenesis." (PMID 37680708, 2023). "Binds to the PAS-B subdomain of HIF1a and HIF-2α thereby preventing the binding to HIF1b, an effect that results in reduced VEGF production and tumor growth." (PMID 37600803, 2023). "It has also been shown that HIF-1α upregulates PDL-1 expression on MDSCs and tumor cells, contributing to cancer immune evasion." (PMID 37047482, 2023). "Even under normoxic conditions, copper can directly increase the stability of HIF-1α, which in turn promotes the expression of target genes such as vascular endothelial growth factor(VEGF), leading to tumor angiogenesis." (PMID 36882769, 2023). "Higher protein expression of HIF-1α (P = 0.0012) and CAIX (P < 0.0001) was observed in hypoxia high versus low tumours." (PMID 37085598, 2023). "Previous findings have shown that tumor cells increase PD-L1 expression through transcription factors such as IRF1/4, c-Myc, EGR1, c-Jun, HIF-1α, NF-κB, ATF3 and STAT3." (PMID 36854755, 2023). "While HIF-2A knockdown resulted in little difference, HIF-1A depletion rescued the decreased expression, consistent with the accumulation of HIF-1A in KIRC tumor tissues." (PMID 37596681, 2023). "Hypoxia-inducible factor 1-alpha (HIF-1α) accumulates and leads to a range of adaptive processes, such as metabolic changes, tumor plasticity, immune evasion, angiogenesis, and metastasis." (PMID 37349288, 2023). "SLC25A37 mediated by the PINK1-PARK2 pathway increases mitochondrial iron accumulation, which leads to the HIF1A-dependent Warburg effect and AIM2-dependent inflammasome activation in tumor cells." (PMID 36937929, 2023). "Autophagy also upregulates HIF-1a, which produces VEGF and is responsible for tumor vascularization in patients with pancreatic cancer." (PMID 37893079, 2023). "The upregulation of HIF-1α and VEGF in the setting of chronic hypoxia was observed in a preclinical study of HCC rat models, resulting in tumor growth." (PMID 37345074, 2023). "In this context, several authors have postulated that CAIX may provide a more reliable marker of hypoxia in tumours than HIF-1α, given its strong regulation by hypoxia-related processes and long half-life after hypoxic induction, allowing for the identification of chronically hypoxic tumour areas." (PMID 37166494, 2023). "HIF-1α target genes, including GLUT1, HK2, PDK1, PFKFB, and VEGFA, are pivotal in regulating tumor metabolism, metastasis, and angiogenesis." (PMID 37906252, 2023). "VEGF–STAT3, which is directly downstream of HIF1α,is crucial for tumor development.The Western blot analysis revealed that the deletion of SHMT2 impaired the HIF1α expression, which consequently impacted the VEGF–STAT3pathway downstream." (PMID 37108312, 2023). "This in vivo study showed that, in contrast to propofol, sevoflurane exposure resulted in bigger ex vivo tumour size, shorter survival time, higher HGF and HIF1α expression, and lower TIMP-2 expression than propofol injection." (PMID 35953652, 2023).
tumor (continued). "Intraperitoneal AgNPs treatment beginning on the day of tumor inoculation enhanced mice survival, reduced the proliferation of ascitic EAC cells, and suppressed the activity of HIF1α, TNF-α and VEGFa genes." (PMID 37111584, 2023). "In tumor cells, YAP and HIF-1α can bind to each other and stabilize HIF-1α proteins in the nucleus, forming the YAP-HIF-1α complex." (PMID 38074679, 2023). "As a potential solution, rCBV was able to predict differences in IDH1 mutation and MGMT status, and tissue from hypercellular and hypervascular microfoci revealed greater expression of Ki‐67, HIF‐1a, CD31, and EGFR compared to tumor background." (PMID 36866773, 2023). "In the current study, we report that treatment of echinomycin dramatically regresses cell growth both in vitro-cultured KSHV + tumor cells and in vivo KS or PEL xenograft mice models, through simultaneously inhibiting Myc and HIF1α expression." (PMID 37143124, 2023). "To further investigate the potential of inhibiting the tumor-promoting effects of THCA by blocking HIF-1α expression, we used the HIF-1α inhibitor CAY10585 in BCPAP and BHT101 cells." (PMID 37718440, 2023). "Plasmacytoid DCs were proposed to be attracted to the tumor microenvironment through the CCL20/CCR6 axis or the hypoxia and hypoxia inducible factor-1α (HIF-1α) pathway." (PMID 37958800, 2023). "When HIF1A and EPAS1/HIF2A are hydroxylated, they are recognized by VHL, a tumour suppressor gene responsible for von Hippel–Lindau disease." (PMID 38276269, 2023). "In the hypoxic tumor microenvironment, elevated NRP1 expression was mediated by transcriptional regulation of HIF1α." (PMID 36841806, 2023). "VDAC1 and GRP78 have been identified as receptors for PK5 to mediate anti-angiogenesis by down-regulating HIF-1α/VEGF, and induce tumor cell apoptosis in hypoxic condition." (PMID 36793021, 2023). "More importantly, cytokines produced by tumor cells, such as VEGF, FGF, HIF-1α, and interleukin 6 (IL-6), have been shown to promote MDSC accumulation and are associated with therapeutic resistance." (PMID 36769116, 2023). "Reduced HIF1A but conversely elevated VHL abundance was measured in both eWAT and iWAT from 4T1/miR-204 KO mice comparing tumour bearing mice." (PMID 37620316, 2023). "Notable promising approaches include tumor-targeted lipid-based CRISPR/Cas9 delivery and nanoparticle-based delivery of HIF-1α inhibitors such as lificiguat." (PMID 37760464, 2023). "Low TIL density in the invading tumor front was related with larger tumor size (p = 0.05), deep invasion (p = 0.01), high smooth-muscle actin (SMA) expression (p = 0.01), and high HIF1α and LDH5 expression (p = 0.04)." (PMID 36900270, 2023). "For example, in nasopharyngeal carcinoma, exosomes from EBV-positive tumor cells are rich in Hypoxia-inducible factor-1α (HIF-1α), which effectively enhances the migration and invasion of EBV-negative tumor cells." (PMID 37848835, 2023). "The HIF1AN inhibits hypoxia-inducible factor 1α (HIF1α), and the downregulation of HIF1AN promotes tumor angiogenesis, cell invasion and proliferation." (PMID 38309281, 2023). "HIFs are transcription factors (TFs) composed of key members such as HIF-1α, HIF-2α, HIF-3α, and HIF-β, which regulate tumor proliferation, angiogenesis, and metastasis through hypoxia-induced signaling pathways." (PMID 37576900, 2023). "A large number of studies have found that hypoxia-induced HIF-1α can effectively promote transcriptional activation and expression of VEGF, providing a basis for tumor growth, local invasion, and distant metastasis." (PMID 37114130, 2023). "The differentiation of Th17 cells is increased through the expression of HIF-1α by IL-6 and TGF-β collaboratively and they can promote tumor growth through angiogenic and immunosuppressive effector functions." (PMID 37501379, 2023).
tumor (continued). "Based on the results of our study, we conclude that GLUT1 and HIF-1α immunohistochemical expressions influence FDG accumulation, with tumor size being the other and most important factor, and SCCs tend to have higher GLUT1 and HIF-1α expressions than ACs." (PMID 37445752, 2023). "HIF-1α and hypoxia-related genes, such as EPAS1, are highly expressed in various hypoxic tumor tissues, which play an important role in tumor angiogenesis, metabolism, and immunity." (PMID 37064872, 2023). "SKA3 overexpression accelerated tumour growth, while these changes were partly reversed by PARP1 and HIF-1a knockdown." (PMID 37821935, 2023). "CCL28 upregulation is under the control of HIF-1α, and the alleviation of hypoxia by TVN will reduce HIF-1α, abrogating CCL28 tumor-promoting effects, which leads to the inhibition of tumor growth." (PMID 37631236, 2023). "PGAM1 regulates Hypoxia-inducible factor 1α (HIF-1α) and PI3K/Akt/mTOR pathways that in turn can provide required energy for proliferation, invasion, and metastasis of tumor cells." (PMID 37501157, 2023). "We quantified the expression of glycolytic markers, HIF-1α, GLUT1 and HK2 as a percentage of total neutrophils determined by CD15 + CK- cells in the tumor sections and adjacent matched normal tissues." (PMID 36614196, 2023). "For example, in GBM tumor cells, IL-1β induces an HIF1A/IL-1β autocrine loop via activating Wnt-1 and RAS, which both contribute to the increase of HIF-1A." (PMID 37538397, 2023). "Other studies have found that sorafenib triggers a switch from HIF-1α-dependent to HIF-2α-dependent pathways, promoting the expression of VEGF and cyclin D1, thus enhancing sorafenib resistance and tumor growth." (PMID 37576900, 2023). "Incorporating the oxygen-sensitive domain of HIF-1α ODD into the CAR scaffold, termed HIF-CAR, HiCAR, and HypoxiCAR, enabling CAR T-cells to induce local cytotoxic effects on tumor cells." (PMID 37020537, 2023). "Previous studies have shown that in various tumours, including CCA, HIF-1a is degraded in a manner that is dependent on the ubiquitin proteasome system (UPS)." (PMID 37821935, 2023). "Mechanistically, TH-302 NPs reduced the expression of HIF-1α and PD-L1, facilitated the infiltration of CD8+ T cells and increased the levels of TNF-α, IFN-γ, and granzyme B in tumours, thereby enhancing the efficacy of α-PD-1 therapy." (PMID 37993847, 2023). "The mounting investigation has revealed that HMGA2 levels are increased during tumor malignancy, and HIF-1α and VEGF are among the downstream genes that are induced by HMGA2, and trigger tumor cell migration." (PMID 37924077, 2023). "In malignant melanoma, targeted inhibition of HIF-1α induced high levels of CCL2 and CCL5 expression and then increased the invasion of tumor-killing NK cells, CD3+, CD4+, and CD8+ T cells in tumor tissues." (PMID 36675491, 2023). "In the tumor tissues, STAT3 phosphorylation was strengthened, and HIF-1A expression was distinctly upregulated in the TRIM14 overexpression group compared to the vector group (p < 0.05)." (PMID 37628777, 2023). "Continuous efforts have been made to target KRAS, HIF1A, and YAP1 because of their roles in tumor initiation." (PMID 37990271, 2023). "Furthermore, research has indicated that hypoxia-inducible factor (HIF)-1α, which is a transcription factor, may have a significant impact on tumor growth and metastasis through its regulation of angiogenesis and lymphangiogenesis, which enables cellular survival in hypoxic conditions." (PMID 37509650, 2023). "Another study has highlighted that the knockout of HIF1α in GBM cells eradicates cell invasion in vitro and inhibits tumor growth in vivo." (PMID 37382594, 2023). "Importantly, the activation of CA9 expression depends on the HIF-1α transcription factor activation cascade, which has been identified as a hypoxia-dependent gene that is relevant for the stem cell niche in GB, in which GB cells or GSCs can survive tumor-targeted therapies." (PMID 38139457, 2023).
tumor (continued). "The HIF-1α/VEGF/VEGFR pathway is currently considered to be related to angiogenesis and tumor progression in a variety of tumors." (PMID 38053093, 2023). "Since it has been shown that endocan supports tumor progression and promotes angiogenesis within the tumor by modulating VEGF-A and HIF-1α expression and signaling, we studied the effect of endocan knockdown on VEGF-A, VEGFR-2, HIF-1α mRNA expression." (PMID 37175885, 2023). "In colorectal cancer, chemotherapy induces ROS activation of HIF1α, which drives the transcription of high-mobility group protein B1 (HMGB1) in tumor cells, thereby promoting macrophage infiltration in tumors." (PMID 37004014, 2023). "Thus, small molecules HIF-1α inhibitors could show significant anti-tumour effects in NPC." (PMID 37558230, 2023). "The potential regulatory mechanism is associated with some critical signaling molecules involved in tumor metastasis, invasion, and matrix reconstruction, such as vascular endothelial cadherin (VE‐cadherin), VEGFA, EphA2, PI3K/AKT signals, MMPs, and HIF‐1α." (PMID 36708044, 2023). "Then, HIF-1α enabled the transcription of WISP3, and subsequently promoted the activation of Wnt signaling pathway, and finally enhanced the tumor growth, metastasis, and angiogenesis in NSCLC." (PMID 37468964, 2023). "FASN inhibitors, also significantly reduce the tumor volume and angiogenesis by downregulation of VEGF and HIF-1α." (PMID 38139462, 2023). "In animal and clinical studies, HIF-1α and HIF-2α have been reported to participate in tumor growth, angiogenesis, and metastasis." (PMID 37460927, 2023). "When exposed to hypoxia, tumor cells as well as stromal and immune components of the TME upregulate hypoxia inducible factor 1 subunit alpha (HIF-1α), a transcription factor that in turn modulates cell metabolism, differentiation, and activation." (PMID 37298470, 2023). "Published reports strongly suggests that HIF-1α directly binds to the promoter region of CD24 and induces CD24 overexpression which further accelerates tumor formation and metastasis." (PMID 37492478, 2023). "The regulation of ARG1 expression in MDSCs by IL-4, HIF-1α, and STAT3 is well established; however, the factors which regulate ARG2 in tumour cells have received less attention to date." (PMID 35962843, 2023). "Considering angiogenesis, the main HIF-1α target genes include VEGF, angiopoietin 1 and 2 and metalloproteases, leading to the formation of new, albeit unstructured, vessels within the tumor." (PMID 37374319, 2023). "We also determined the hypoxia indicators HIF-1α and HIF-2α expression in each tumor subgroup by immunohistochemistry." (PMID 37324455, 2023). "When VHL is genetically inactivated, HIF1α and HIF2α become stabilized, which leads to changes in cellular metabolism, angiogenesis, epithelial-mesenchymal transition (EMT), invasion, and tumor metastasis that contribute to the progression of ccRCC." (PMID 37190141, 2023). "Comparison of the TAL and RMC populations from the treated tumour revealed a transcriptional switch from high HOXB9 and TFCP2L1 activity in TAL1 cells, to high MYC, HIF1A, YY1 and NFE2L2 activity in RMC cells." (PMID 37236926, 2023). "As such, we further examined hypoxic markers through immunohistochemical staining and found that HIF-1α, CA-IX, and GLUT-1 staining was increased in the core compared to the tumor edge." (PMID 37752585, 2023). "After this, by knocking out with the CRISPR-Cas9 system the HIF-1α and HIPK2 genes individually or simultaneously, the authors determined the in vivo tumor growth capacities of Hepa1-6 cells in a xenograft mice model." (PMID 36900356, 2023). "Impeding the catalytic activity of PHDs may stabilize HIF-1a and activate HIF-1a-mediating transcriptional pathways, which can in turn promote cellular adaptation to hypoxic conditions and the transcription of oncogenic genes, thus leading to tumor progression." (PMID 37936981, 2023).
tumor (continued). "We found that HIF-1α-high PDACs and GLUT1-high PDACs had a larger tumor size and were more prone to lymph node metastasis." (PMID 37892091, 2023). "Overexpression of UBE2S promotes tumor cell proliferation and migration by regulating the VHL/HIF-1α/STAT3 signaling pathway." (PMID 38115063, 2023). "To further demonstrate the effectiveness of coexposure, we monitored the changes in several pivotal factors in the tumor microenvironment, including COX-2, β-catenin, HIF-1α, and p16 via protein immunostaining of the livers of mice in each group." (PMID 37762463, 2023). "In this study we observed, the presence of macrophages in the TME lead to alterations in the expression of HIF-1α, heat shock protein 70 (HSP70), and cysteine proteases cathepsin B and L which is often to correlate with poor prognosis in pathological tumour." (PMID 38062442, 2023). "Cytoplasmic or nuclei expression of HIF-1α and VEGF-A and nuclei expression of Ki67 were observed mainly in the tumor cells of LACC samples." (PMID 37335690, 2023). "HIF-1α target genes, such as VEGF-A and VEGF-C, are involved in tumor angiogenesis and lymphangiogenesis, leading to lymph node metastasis and recurrence." (PMID 36745547, 2023). "For HIF1A, ETS1, and VEGFR2, we detected significant protein levels in FAP-overexpressing tumor samples." (PMID 36672341, 2023). "HIF-1α modulates tumor cell metabolism through its dependent genes (GLUTs, VEGF, etc.)promoting adaptation of tumor cells to hypoxia and stimulating angiogenesis." (PMID 37542119, 2023). "Lines of evidence demonstrate that functions of HIF‐1α and HIF‐2α vary depending on the cell type of tissue or tumor." (PMID 37334735, 2023). "Therefore, tumor cells may leverage the HIF-1α/PD-L1 axis to evade from immune surveillance." (PMID 36747292, 2023). "Intriguingly, the hypoxia-associated pathway upregulates the expression of PD-L1 in malignant cells via HIF-1α and HIF-2α, thus promoting immune tolerance within the tumor microenvironment." (PMID 37958373, 2023). "Western blotting revealed that apatinib significantly promotes mTOR phosphorylation in mouse tumor tissues, while FMD treatment leads to a significant inhibition of mTOR phosphorylation and HIF-1α expression." (PMID 37884960, 2023). "HIF‐1α promotes the expression of VEGF, which leads to tumor angiogenesis and increases metastatic potential." (PMID 37227584, 2023). "The hypoxic microenvironment stimulates HIF-1α in tumor cells, leading to higher expression of angiogenic factors like VEGF and bFGF, which promote tumor formation and vascularization." (PMID 37964867, 2023). "Functional studies have revealed that ectopic expression of PHD1 suppresses accumulation of HIF1α and that carcinoma cells expressing PHD1, which were injected into mice, inhibited tumor growth though increased necrosis and decreased microvessel density." (PMID 36976352, 2023). "Wnt3a/β-catenin, circSATB2, HIF-1α/COX-2, and LMO7 in tumor-derived EV modulate genes or signaling pathways promoting the successful proliferation and migration of tumor cells." (PMID 36829523, 2023). "The Western blot results further confirmed that the expressions of HIF1α, VEGFA, and p-STAT3 were all reduced in the tumor tissue of the shSHMT2 group." (PMID 37108312, 2023). "SLC7A11 upregulation promotes HIF-1α expression by reducing α-ketoglutarate (αKG) levels, which in turn promotes the expression of programmed death ligand 1 (PD-L1) and CSF1 in tumor cells." (PMID 37663266, 2023). "LW6 inhibited tumor angiogenesis, down-regulated the expression of PD-L1, and promoted the apoptosis of HCC cells by inhibiting HIF-1α." (PMID 38155974, 2023). "While the hypoxic tumor microenvironment generates abnormal new blood vessels through both tumor-induced and CAF-induced factors, it also is a necessary factor for the conversion of NFs to CAFs, mediated through HIF1α-induced NFκB, CCL5, COL1A2, and αSMA." (PMID 37046676, 2023).